ALB (albumin)
Diseases named in the same sentence as ALB in open-access papers (continued):
Sharing a sentence is not in itself a finding about the gene and the disease.
type 2 diabetic nephropathy (8 papers, 2011 to 2024). "Our present observations suggest febuxostat suppresses urinary albumin and glomerular injury at early stages of type 2 diabetic nephropathy, i.e., at the stage when inflammatory cytokines, such as IL-6 and MCP-1, are secreted." (PMID 31546603, 2019). "A recent clinical trial demonstrated that atrasentan exhibited additive effects in decreasing the urine albumin-to-creatinine ratio in patients with type 2 diabetic nephropathy who were receiving ACEIs or ARBs." (PMID 25300759, 2014). "In patients with type-2 diabetic nephropathy receiving ACEIs and/or ARBs, treatment with atrasentan produced an additive effect in decreasing the urine albumin-to-creatinine ratio." (PMID 25300759, 2014).
Urinary incontinence (8 papers, 2018 to 2025). Loss of the ability to control the urinary bladder leading to involuntary urination. "Our analysis revealed that preoperative urinary incontinence, higher albumin levels and surgery performed by inexperienced surgeons were associated with a delayed recovery from PUI." (PMID 36901096, 2023). "We also found that preoperative urinary incontinence, higher albumin levels and surgery performed by unexperienced surgeons were associated with delayed PUI recovery, while nerve sparing was significantly associated with early recovery." (PMID 36901096, 2023). "RAPS scale includes 13 risk factors: physical activity, mobility, food intake/nutrition, fluid intake, incontinence/moisture, general physical condition, fractioning/shearing, sensory perception, weight/body constitution, type of skin, body temperature, serum-albumin, blood pressure." (PMID 40713677, 2025).
urolithiasis (8 papers, 2014 to 2025). Stone(s) within the urinary tract. "Blood sample results showed that patients with urolithiasis had significantly higher levels of indirect bilirubin, total protein, albumin, blood urea nitrogen, and serum creatinine than those without urolithiasis (P < .05)." (PMID 41204506, 2025). "Researchers found that albumin and immunoglobulins were the most expressed proteins in the urine of urolithiasis patients, and the ratio of albumin to unidentified p24 proteins was higher in the urine of urolithiasis patients compared with controls." (PMID 32509863, 2020). "GWAS data for estimated glomerular filtration rate from serum creatinine (eGFRcrea), urine albumin–creatinine ratio (uACR), and CKD were obtained from the CKDGen Consortium, and GWAS data for urolithiasis were obtained from the FinnGen consortium." (PMID 37173785, 2023).
urothelial carcinoma (8 papers, 2018 to 2026). A malignant neoplasm derived from the transitional epithelium of the urinary tract (urinary bladder, ureter, urethra, or renal pelvis). "A growing number of studies have regarded the preoperative serum albumin-to-globulin ratio (AGR) as a prognostic indicator of urothelial carcinoma (UC) following radical surgery." (PMID 36105255, 2022). "Preoperative serum albumin has been considered to be closely correlated with the prognosis of various cancers, including urothelial carcinoma (UC)." (PMID 29685957, 2018). "We evaluated the prognostic significance of the Lactate Dehydrogenase-to-Serum Albumin Ratio (LAR), Fibrinogen-to-Albumin Ratio (FAR), and Platelet-to-Lymphocyte Ratio (PLR) in patients with high-grade urothelial carcinoma (HGUC) of the bladder who underwent radical cystectomy (RC)." (PMID 40134599, 2025). "Although the albumin-to-globulin ratio (AGR) is a promising biomarker, no study has investigated its prognostic significance for advanced urothelial carcinoma (UC)." (PMID 34341416, 2021).
valvular heart disease (8 papers, 2018 to 2025). "The univariate logistic regression analysis showed that age, valvular heart disease, and albumin were associated with mortality in surgical patients with ECMO implantation treated with CRRT." (PMID 37982218, 2023). "In surgical patients on combined CRRT and ECMO, age, valvular heart disease, and albumin were the independent risk factors for prognosis." (PMID 37982218, 2023). "Additionally, prior studies have shown that age, valvular heart disease, serum albumin levels, and APACHE II and SAPS II scores were associated with the prognosis of ECMO and CRRT treatments." (PMID 39632252, 2024). "There were significant differences between the non-survivors and survivors in body mass index (BMI), the presence of moderate to severe valvular heart disease, albumin concentration, the American Society of Anesthesiologists (ASA) classification, and the SAS." (PMID 32025941, 2018). "In surgical patients on combined CRRT and ECMO, age, lack of valvular heart disease, and albumin were the independent risk factors for prognosis." (PMID 37982218, 2023). "The multivariate logistic regression analysis showed that age (OR 1.064 per year, 95% CI 1.005–1.127, p = .034), valvular heart disease (OR 0.117, 95% CI 0.024–0.571, p = .008), and albumin (OR 0.804 per g/L, 95% CI 0.685–0.944, p = .008) remained the independent risk factors for prognosis." (PMID 37982218, 2023). "In the subset of patients on combined CRRT and ECMO, independent risk factors for mortality included higher age, lack of valvular heart disease, and lower serum albumin." (PMID 37982218, 2023). "The AUC value to predict the 90-day mortality was 0.70 for ASA ≥ 3 only, 0.71 for SAS ≤ 6 only, 0.81 for SAS ≤ 6 combined with ASA ≥ 3, and 0.85 for SAS ≤ 6 combined with albumin concentration < 3.5 g/dl, BMI ≤ 20, and the presence of moderate to severe valvular heart disease." (PMID 32025941, 2018).
ventilator-associated pneumonia (8 papers, 2012 to 2025). Serious INFLAMMATION of the LUNG in patients who required the use of PULMONARY VENTILATOR. "Adjusting perioperative serum albumin levels and tailoring treatment strategies for high-risk patients may help reduce the incidence of complications, such as ventilator-associated pneumonia, and improve outcomes following heart valve surgery." (PMID 40248251, 2025). "This study aims to investigate the relationship between the difference in hematocrit and albumin (HCT-ALB) and ventilator-associated pneumonia (VAP) among patients undergoing continuous mechanical ventilation." (PMID 41244105, 2025).
acute aortic dissection (7 papers, 2019 to 2026). "This study found that the most significant factors affecting mortality were treatment methods, the type of acute aortic dissection, and levels of ischemia-modified albumin." (PMID 37835873, 2023). "This work explored the prognostic prediction capabilities of ischemia-modified albumin (IMA) in patients suffering from acute aortic dissection (AAD)." (PMID 31680992, 2019). "The significant factors positively related to dropout from OCR program were age < 65 years, male, albumin ≦ 3.8 g/dl, CABG, valvular surgery, aortic dissection as well as longer road distance (≧ 20 km)." (PMID 33248454, 2020).
amyotrophic lateral sclerosis (7 papers, 2012 to 2025). Amyotrophic lateral sclerosis (ALS) is a neurodegenerative disease characterized by progressive muscular paralysis reflecting degeneration of motor neurons in the primary motor cortex, corticospinal tracts, brainstem and spinal cord. "A cohort study determined that albumin levels were significantly related to worse clinical outcomes when diagnosing amyotrophic lateral sclerosis." (PMID 38864919, 2024). "Additionally, lower serum albumin levels at the time of amyotrophic lateral sclerosis (ALS) diagnosis were linked to a higher mortality risk, and another study reported increased survival in ALS patients with higher serum albumin levels." (PMID 39206288, 2024). "In a recent study of individuals with amyotrophic lateral sclerosis, the authors showed higher choroid plexus volumes compared to healthy controls and found a significant positive correlation between choroid plexus volume and CSF/serum albumin ratio (as a proxy for BCB disruption)." (PMID 40529789, 2025). "This study posits that biochemical blood parameters, including total protein, albumin, urea, creatinine, transferrin, and overall lymphocyte count, may serve as an effective tool for assessing the nutritional status of patients with amyotrophic lateral sclerosis (ALS)." (PMID 38313408, 2023). "Researchers have observed a reduction in body mass index (BMI), as well as some deterioration in nutritional status indicators, along with decreased levels of total protein, albumin, urea, and creatinine in the blood of patients with amyotrophic lateral sclerosis (ALS)." (PMID 38313408, 2023). "Specific proteins, e.g., α-synuclein (α-syn) and clusterin in Parkinson ́s disease (PD); creatinine, human serum albumin (HSA), and TAR DNA binding protein 43 kDa (TDP-43) in amyotrophic lateral sclerosis (ALS); as well as RNAs’ biomarkers have been discovered in biofluids." (PMID 36614231, 2023).
aortic valve stenosis (7 papers, 2020 to 2026). Aortic valve stenosis (AVS) is a condition characterized by narrowing of the heart's aortic valve opening. "Stenosis patients were predominantly male and had lower albumin, whereas other demographic and laboratory findings were similar." (PMID 41340380, 2025). "Other limitations include a lack of objective measures of stricture improvement, and although laboratory markers such as CRP, ESR, and albumin were measured, changes in these measures were not specifically reported for the stricture group." (PMID 36895272, 2023).
calcification (7 papers, 2016 to 2024). Process by which organic tissue becomes hardened by the physiologic deposit of calcium salts. "Decreased albumin levels are strongly associated with chronic inflammation and vascular calcification." (PMID 37799589, 2023).
candidiasis (7 papers, 2014 to 2025). Infection with the organism Candida. "This biomarker has a sensitivity of 92% and a specificity of 81% for the diagnosis of invasive candidiasis, However, the risk of false positives has been evidenced in patients receiving albumin, intravenous immunoglobulin, and systemic antimicrobials." (PMID 40872317, 2025). "Children diagnosed with candidiasis consistently exhibited lower serum levels of vitamin D, iron, zinc, albumin, and vitamin A compared to their healthy peers." (PMID 40507084, 2025). "Despite intentionally maintaining moderate differences between the case and control groups, significant reductions were observed in serum vitamin D, iron, zinc, albumin, and vitamin A in children diagnosed with candidiasis." (PMID 40507084, 2025). "Our investigation revealed that individuals suffering from SS oral Candida infection had elevated blood leukocyte counts, decreased serum albumin levels, and reduced levels of the serum immunoglobulins IgG, IgA, and IgM." (PMID 39020326, 2024). "ALB can affect immunity to candidiasis in humans via different ways." (PMID 38003833, 2023). "Therefore, the role of albumin during candidiasis requires further in-depth clinical and mechanistic elucidation to identify whether it can serve as a biomarker or can be used for therapy." (PMID 34154403, 2021). "Furthermore, the patients with persistent candidiasis had higher albumin levels at baseline than the individuals without candidiasis (p = 0.04)." (PMID 25338733, 2014).
chronic kidney failure (7 papers, 2020 to 2025). "Increased glycated albumin levels are associated with the development of vascular complications in diabetic patients, particularly those with chronic kidney failure who undergo hemodialysis." (PMID 37370930, 2023). "The risk score used in this study, which includes blood loss, medication at admission, and postoperative serum albumin, showed good predictive values for an increased risk of acute-on-chronic kidney failure in geriatric patients." (PMID 37646924, 2023). "Although relatively large ORs were obtained for several baseline factors in the univariate analyses, including UPCR ≥ 0.15 (3.31; p = 0.068), chronic kidney failure (2.50; p = 0.282), and serum albumin ≤ 3.5 g/dL (1.92; p = 0.203), none of the variables were statistically significant." (PMID 41375027, 2025).
coronary artery stenosis (7 papers, 2017 to 2025). "In contrast, albumin plays a protective role by inhibiting platelet activation and aggregation, thereby contributing to the prevention of platelet-induced coronary artery stenosis." (PMID 40755644, 2025). "In addition, decreased albumin levels were found to be associated with increased blood viscosity, impaired endothelial function, increased platelet activation and aggregation, and increased synthesis of important mediators of platelet-derived coronary artery stenosis." (PMID 40531765, 2025). "Serum albumin inhibits platelet activation and aggregation, and low levels of it can contribute to platelet-induced coronary artery stenosis." (PMID 38152782, 2023). "As serum albumin inhibits platelet activation and aggregation, low levels of it can contribute to platelet-induced coronary artery stenosis." (PMID 38152782, 2023). "Our study showed that there were significant difference in plasma albumin levels between the high GS group, MI group and multi-vessel disease subgroups, indicated the relationship between ALB and severity of coronary stenosis in patients with ACS." (PMID 34876026, 2021). "In the studied population, the severity of coronary stenosis, quantified as Gensini score, was positively correlated with FBG, PBG, glycated albumin, and HbA1c even after adjustments for all known factors." (PMID 29079813, 2017).
Dent disease (7 papers, 2017 to 2024). Dent disease is a rare genetic renal tubular disease characterized by manifestations of proximal tubule dysfunction. "We also showed that megalin- and cubilin-mediated uptake of albumin is coordinately altered in our cell culture model of Dent disease." (PMID 38562767, 2024). "However, combined with normal albumin levels, urine examination and urinary ultrasound, renal tubular disease such as Dent disease should be considered first." (PMID 38915441, 2024). "Increased urinary albumin and low molecular weight protein excretion (alpha-1 microglobulin, beta-2-microalbumin, retinol-binding protein) might be a clue to Dent’s disease—the urine dipsticks test may be negative as it detects albumin rather than low molecular weight protein." (PMID 33660084, 2021).
hemophilia A (7 papers, 2017 to 2024). The most common form of hemophilia characterized by spontaneous or prolonged hemorrhages due to factor VIII deficiency. "After 5 months of transplantation (Tx) of eGFP-expressing Lin- BMCs from female to hemophilia A (HA) male mice, the immuno-histochemical analysis of liver sections revealed the presence of donor-derived cells expressing hepatic markers, like albumin and HNF4α." (PMID 28328977, 2017).
hilar cholangiocarcinoma (7 papers, 2017 to 2026). A cholangiocarcinoma that arises from the junction, or adjacent to the junction, of the right and left hepatic ducts. "Overall, hilar cholangiocarcinoma is associated with a poor prognosis and the data demonstrated that an albumin level >3.0 g/dL at presentation is an independent predictor of overall survival." (PMID 27389416, 2017). "Preoperative lactate dehydrogenase-to-albumin ratio (LAR) is an independent prognostic factor in patients with hilar cholangiocarcinoma after radical resection." (PMID 41255598, 2025). "The prognostic role of GGT has only been reported in combination with chemotherapy, hepatectomy or transcatheter arterial embolization in ICC and the relevance of reduced albumin was only described with regard to hilar cholangiocarcinoma." (PMID 36358743, 2022). "Recently, high serum albumin was also found to confer a survival advantage in patients with hilar cholangiocarcinoma." (PMID 33101412, 2020). "Serum albumin is inexpensive and reproducible, and nearly all patients with biliary pathology or suspected hilar cholangiocarcinoma will have a hepatic panel measured." (PMID 27389416, 2017). "Besides, Saito and colleagues have reported that a prognostic scoring system, consisting of PLR, CRP, ALB and CEA, could predict the postoperative survival after resection of perihilar cholangiocarcinoma." (PMID 33676467, 2021). "Studies have demonstrated that pre-operative albumin concentration is an independent predictor of survival after surgical resection—a finding that is now extended to the overall survival of all patients presenting with hilar cholangiocarcinoma, regardless of therapeutic management." (PMID 27389416, 2017).
hyperhomocysteinemia (7 papers, 2018 to 2025). A serious metabolic condition caused by mutations in the MTHFR gene, medications, or nutritional deficiency. "The shifts in balances leads to the formation of the poorly eliminable albumin‐bound homocysteine, so oxidative stress could be the cause of possible hyperhomocysteinemia." (PMID 40577064, 2025). "Animal studies indicate that elevated homocysteine levels may result in glomerular damage, and folic acid supplementation lowers plasma creatinine concentration and urinary albumin excretion induced by hyper-homocysteinemia." (PMID 29466283, 2018). "Laboratory tests showed homocysteinemia (HCY) of 22.43 μmol/L, Hb of 98 g/L, mean corpuscular volume (MCV) of 108.1 fL, HCT of 30.50%, albumin of 37.1 g/L, total protein 52.1 g/L, and high neuron-specific enolase (NSE) level of 32.64 ng/mL, indicating hyperhomocysteinemia and macrocytic anemia." (PMID 37795244, 2023).
hypertensive nephropathy (7 papers, 2016 to 2024). Kidney damage that results from chronically elevated blood pressure; complications include glomerular damage resulting in proteinuria and hematuria. "We found that the EPC-MVs alleviated the increase of blood urea nitrogen and urinary albumin excretion and the decrease in creatinine clearance caused by hypertensive nephropathy in vivo." (PMID 36845016, 2023). "Also, miRNAs could serve as modifiable treatment markers as ACE inhibitors or as a β-blocker treatment of hypertensive nephropathy patients with reduced miR-103a-3p and albumin-to-creatinine ratio." (PMID 38804362, 2024). "A recent bioinformatics study on the GSE37455 dataset identified three core ferroptosis-related genes, namely, albumin (ALB), nicotinamide N-methyltransferase (NNMT), and ATF3, that were differentially expressed in hypertensive nephropathy samples compared with normal samples." (PMID 37739961, 2023).
laryngeal carcinoma (7 papers, 2015 to 2025). Carcinoma that arises from the laryngeal epithelium. "More recently, pre-therapeutic indices of systemic inflammation based on CRP and albumin have been found to provide prognostic information in nasopharyngeal and laryngeal cancer patients." (PMID 32182693, 2020). "The CRP/albumin ratio could predict poor survival in patients with hypopharyngeal and laryngeal cancer." (PMID 35847918, 2022). "In addition, the application of free flap reconstruction for pharyngeal defect and postoperative lower albumin status increase the inpatient medical cost among patients who undergo total laryngectomy for laryngeal cancer/hypopharyngeal cancer." (PMID 32673371, 2020). "The aim of this study was to investigate the effects of prognostic nutritional index (PNI), systemic immune inflammation index (SII) and hemoglobin, albumin, lymphocyte, platelet (HALP) score on fistula formation, recurrence and mortality in patients with laryngeal cancer." (PMID 39915316, 2025). "The C-reactive protein (CRP)/albumin (Alb) ratio (CAR) has been identified as a novel inflammation-based prognostic marker in several cancers, including esophageal cancer, lung cancer, hypopharyngeal and laryngeal cancer, and nasopharyngeal cancer." (PMID 33686103, 2021). "Additionally, in more than one proteomics study, cystatin-B, heat shock protein beta-1, and isoform 1 of serum albumin were deemed to be related to laryngeal carcinoma, but without in-depth functional research or clinical validation." (PMID 25874882, 2015).